MYD88 (MYD88 innate immune signal transduction adaptor)
Diseases named in the same sentence as MYD88 in open-access papers (continued):
Sharing a sentence is not in itself a finding about the gene and the disease.
melanoma (continued). "In this study, we established TLR4/MYD88/STAT3 and TLR4/TRIF/STAT3 pathways in melanoma and demonstrated their pathogenic roles." (PMID 32312954, 2020). "Within a melanoma model, the innate myeloid differentiation factor 88 (MyD88) response was determined to be an important factor in the reduction of tumour sizes mediated by VSV." (PMID 32882969, 2020). "A recent study also showed that HMGB1 released from UV-damaged keratinocytes activates TLR4/MYD88-dependent neutrophilic inflammation, which can promote angiotropism and metastasis of melanoma cells." (PMID 29636841, 2018). "TLR4 is also overexpressed in melanoma, colon cancer, and breast cancer, and the expression of its downstream adaptor protein MyD88 is elevated in melanoma and colon cancer." (PMID 29636841, 2018). "In this study, we sought to better define the role of MyD88 in neoplastic cells using a murine melanoma model." (PMID 28662055, 2017). "To investigate the impact of MyD88 intrinsical activity in tumor cells, we used short hairpin RNA (shRNA) lentiviral vectors to reduce endogenous MyD88 levels in B16 melanoma cells." (PMID 28662055, 2017). "Herein, we have demonstrated that MyD88 expression is required to maintain the angiogenic switch that supports B16 melanoma growth." (PMID 28662055, 2017). "Engagement of MyD88 in activated murine melanoma cells triggers an angiogenic program that rely on the secretion of trophic factors for vascular cells, including VEGF, FGF-2, and CXCL15." (PMID 28662055, 2017). "Due to the fact that IL-6 mRNA levels remained unaffected in our study we believe that the mechanism behind WNT5A induced IL-6 release in malignant melanoma cells is Myd88/TLR2 independent." (PMID 24766647, 2014). "Importantly, LTX-315-induced TiDC maturation and the generation of anti-melanoma immunity relied on the presence of the signal transducer MyD88." (PMID 38545099, 2024). "Thus, LTX-315 triggers the generation of anti-melanoma immunity by inducing MyD88-dependent maturation of TiDCs." (PMID 38545099, 2024). "The data presented in this study hint that pDCs impairment in melanoma might result from defective TLR/MyD88-dependent signaling (i.e., IRF7 activation) or from a broad perturbation of their metabolic functions (i.e., glycolysis)." (PMID 38239354, 2023). "Moreover, we detected a considerable inhibition of IRF7 constitutive expression in pDCs after their exposure to SN-mel, providing evidence that TLR/MyD88-dependent signaling in pDCs was inhibited by melanoma secretome." (PMID 38239354, 2023). "MyD88 is a critical protein in Toll-like receptor pathways, and MyD88-/- knockout mice had a decrease in neutrophil infiltration into B16 melanomas that expressed the surrogate antigen chicken ovalbumin, and this correlated with reduced efficacy of the oncolytic virotherapy." (PMID 32882969, 2020). "The importance of T-cell–mediated TLR signaling is emphasized by reversed or delayed tumor growth of B16 melanoma in tumor-bearing MyD88 knockout mice that received adoptive transfer of TCR-transgenic CD8+ pmel T cells, after peritumoral injections of Pam3CSK4 (a synthetic TLR2 agonist)." (PMID 32012718, 2020). "Whether TLR4 signaling activates STAT3 through the MYD88 and TRIF pathways in the two cancer types, as we observed in melanoma, and whether TLR4/STAT3 signaling plays a pathogenic role in the two cancers warrant further investigations." (PMID 32312954, 2020). "MyD88 was expressed in all three cell lines with the highest level in MDA-MB-435 melanoma cells." (PMID 29486738, 2018). "Whereas the number of tumor-infiltrating leukocytes (CD45+) was comparable between the groups, melanomas induced by MyD88 knockdown cells showed a myeloid infiltrate enriched predominantly in CD11b+F4/80+ macrophages and with a lesser percentage of CD11b+Gr1+ cells." (PMID 28662055, 2017).
melanoma (continued). "To ascertain whether factors secreted by B16 cells were involved in tumor angiogenesis, and evaluate whether signaling via MyD88 was required, we explored the influence of conditioned medium from melanoma cells on endothelial cell tube formation." (PMID 28662055, 2017). "In subcutaneous melanoma models, BCG vaccine stimulation of murine melanoma cells demonstrated the critical role of MyD88 signaling in mediating BCG-induced immunotherapy." (PMID 41403926, 2025). "Furthermore, we established a subcutaneous B16-F10 melanoma model for intratumoral BCG treatment and compared wild type mice to TLR2-/-, TLR3-/-, TLR4-/-, TLR7-/-, TLR3/7/9-/-, caspase 1-/-, caspase 11-/-, IL-1R-/-, cGAS-/-, STING-/-, IFNAR-/-, MyD88-/-deficient animals." (PMID 38835781, 2024). "In conclusion, MyD88 impacts on both innate and adaptive responses to BCG leading to an efficient antitumor response against melanoma." (PMID 38835781, 2024). "In an in vivo melanoma model, ultraviolet (UV) irradiation induced a TLR4/MYD88-driven neutrophilic skin inflammatory response initiated by high mobility group box 1 (HMGB1) release from ultraviolet-damaged keratinocytes." (PMID 37525065, 2023). "PTX3, a key factor in a subtype of invasive melanoma, can mediate the expression of the EMT transcription factor TWIST1 through a TLR4/MYD88/IKK/NF-κB signaling pathway and drive melanoma cell migration." (PMID 37277447, 2023). "The TLR4/MYD88/STAT3 and TLR4/TRIF/STAT3 pathways established in this study shed novel insights into the pathophysiology of melanoma, and suggest new, potentially more effective, targets for treating melanoma." (PMID 32312954, 2020). "TLR4 signaling activates STAT3 through MYD88 and TRIF, and subsequently upregulates a series of STAT3 target genes to promote melanoma progression." (PMID 32312954, 2020). "In this study, we demonstrated that activation of TLR4/MYD88/STAT3 and TLR4/TRIF/STAT3 pathways promotes proliferation of cultured melanoma cells." (PMID 32312954, 2020). "Orally administered spirulina extract has been shown to enhance tumoricidal NK activation through the MyD88 pathway, and spirulina exerted a synergistic antitumor activity with BCG-cell wall skeleton when used as immunotherapy of melanoma." (PMID 23213541, 2011). "BCG treatment was not able to control melanoma growth in MyD88-/- mice that presented similar volume as the untreated tumors, differing from BCG response in WT mice." (PMID 38835781, 2024). "For instance, in melanoma, the PI3K/Akt, MyD88, and IKK pathways could be involved in IL-36β-mediated mTORC1 activation, promoting CD8+ T cell activation and inducing antitumor immune responses in vitro and in vivo." (PMID 37046703, 2023). "Second, we found that TLR4 ligands activate STAT3 through MYD88 (myeloid differentiation primary response gene 88) and TRIF (TIR-domain-containing adapter-inducing interferon-β) in melanoma cells and promote STAT3-mediated cellular events in melanoma progression." (PMID 32312954, 2020). "Here, we revealed that melanomas developed from cells lacking MyD88 have an improved infiltration of macrophages to the tumor site." (PMID 28662055, 2017). "Melanomas developed from cells lacking MyD88 showed an enhanced secretion of chemoattractant ligands such as CCL2, CXCL10 and CXCL1 and have an improved infiltration of macrophages to the tumor site." (PMID 28662055, 2017). "No mutation of MYD88, TRIF and STAT3 genes has been reported in melanoma patients." (PMID 32312954, 2020). "In addition to MYD88 and TRIF, other molecules might be involved in the signaling cascades from TLR4 to STAT3 in melanoma." (PMID 32312954, 2020). "Importantly, melanoma growth was no longer inhibited in MyD88−/−Rnf5−/− mice, with MyD88−/− mice exhibiting a tumor growth phenotype between that of the WT and MyD88−/−Rnf5−/− double-knockout mice." (PMID 30940817, 2019).
cardiac hypertrophy (36 papers, 2014 to 2025). "Receptor-interacting serine/threonine-protein kinase 2 (RIP2) deficiency ameliorates cardiac hypertrophy through multiple signaling pathways that reduce TLR4/MyD88/NF-κB activation and MAPKs phosphorylation." (PMID 37113698, 2023). "In the present study, we found that Ang II activated the CaMKII, CnA-NFAT, and MyD88 inflammatory pathways in H9c2 cells and caused myocardial hypertrophy." (PMID 33149757, 2020). "Cardiac hypertrophy is closely associated with the TLR4/MyD88/NF-κB signaling pathway." (PMID 33324685, 2020). "For instance, in cardiac hypertrophy, CHRF interacts with miR-93 and miR-489 to regulate AKT3 and MyD88, promoting myocardial hypertrophy." (PMID 40612103, 2025). "MyD88 leads to CaMK II oxidation and is essential for adverse cardiac hypertrophy and inflammation during myocardial infarction." (PMID 37113698, 2023). "This lncRNA is conserved between humans and mice and acts by sequestering miRNA-489, hence upregulating its downstream target, MYD88, which is a key gene in activating cardiac hypertrophy." (PMID 37762106, 2023). "The expression of MyD88 is a prerequisite for Ang-II to activate cardiac hypertrophy, and MyD88−/− mice reduce inflammatory responses when treated with Ang-II." (PMID 37762106, 2023). "In our study, while MyD88 knockdown yields reduced cardiac hypertrophy after MI and TAC, TRIF apparently has little influence on the development of afterload-induced cardiomyocyte hypertrophy." (PMID 36289897, 2022). "For example, the lncRNA Chrf sequesters miR-489, which targets Myd88 (MYD88 innate immune signal transduction adaptor) in cardiomyocytes to regulate cardiac hypertrophy." (PMID 35893236, 2022). "By sequestering the miRNA-489, this lncRNA prevents the interaction of the microRNA with its target Myd88 (myeloid differentiation primary response gene Myd88), an indispensable gene in the regulation of cardiac hypertrophy." (PMID 34698215, 2021). "The mechanism by which TLR4 influences myocardial hypertrophy mainly involves the MyD88-dependent pathway and MMP9-dependent pathway." (PMID 35046797, 2021). "MyD88 is a prerequisite for Ang‐II to initiate cardiac hypertrophy, and mice with MyD88 knockout have reduced inflammatory response to Ang‐II." (PMID 32969576, 2020). "Overall, these results suggest that the TLR4/MyD88/NF-κB pathway is a bridge between RAS, SNS and hypertension, and provides a novel treatment therapeutic for hypertension and cardiac hypertrophy caused by hypertension." (PMID 33324685, 2020). "For example, lncRNA CHRF was reported to regulate cardiac hypertrophy together with miR-489 and Myd88." (PMID 31913855, 2020). "For instance, LM8-mediated MyD88 inhibition reportedly exerts beneficial effects for cardiac hypertrophy and fibrosis by reducing inflammatory cytokine expression as well as immune cell infiltration in obese mouse models." (PMID 33324685, 2020). "Previously, we demonstrated a function of AS-1 in attenuating TAC-induced cardiac hypertrophy through inhibiting IL-1R-mediated MyD88-dependent signaling." (PMID 31015570, 2019). "Other two studies showed that Myd88-mediated inflammatory signaling leads to CaMKII oxidation, cardiac hypertrophy, and death after MI and blockade of Myd88 with ST2825 or IMG2005 prevents left ventricular dilation and hypertrophy after acute MI." (PMID 29576748, 2018). "Cardiac Hypertrophy-Related Factor (CHRF), another lncRNA, is able to directly bind to miR-489 and regulate the expression of MyD88 (myeloid differentiation primary response gene 88, as a miR-489 target) and consequent cardiac hypertrophy." (PMID 30013975, 2018). "For instance, lncRNA-CHRF regulates cardiac hypertrophy by competitively binding miR-489 that regulates Myd88 expression." (PMID 28198439, 2017). "For example, lncRNA CHRF up-regulates Myd88 expression and cardiac hypertrophy by directly binding miR-489." (PMID 27270310, 2016).
cardiac hypertrophy (continued). "LncRNA-CHRF acts as an endogenous sponge of miR-489, which down-regulates miR-489 expression levels and regulates the expression of differentiation primary response gene 88 (Myd88) and cardiac hypertrophy." (PMID 26078353, 2015). "For example, a cardiac hypertrophy-associated lncRNA, CHRF, acts as an endogenous sponge of miR-489, which can directly bind to miR-489 and regulate its target gene, Myd88, expression and hypertrophy." (PMID 25760077, 2015). "Another lncRNA cardiac hypertrophy-related factor (Chrf) was shown to sequester miR-489 to inhibit its action of targeting myeloid differentiation primary response gene 88 (Myd88), which induces cardiac hypertrophy through the NF-κB system." (PMID 26445043, 2015). "TLR4/MYD88 has been shown to have a critical role in NF-κb-mediated cardiac hypertrophy and inflammation." (PMID 25546437, 2014). "Previous studies also show that both pharmacologic and genetic inhibition of MYD88 attenuate cardiac hypertrophy and apoptosis in myocardial infarction and pressure-overload mouse models in a TLR-NF-κb dependent manner." (PMID 25546437, 2014). "Since MYD88 has been shown to be involved in NF-κb p65 activation and cardiac hypertrophy, we measured MYD88 expression in HFD fed mice." (PMID 25546437, 2014). "Knockout of MYD88 further attenuates cardiac hypertrophy, inflammation and cell apoptosis via inhibition of NF-κb signaling pathway in post-myocardial infarction." (PMID 25546437, 2014). "Thus, CHRF functions as an endogenous sponge to inhibit miR-489 activity and affect MyD88 levels, contributing to myocardial hypertrophy." (PMID 40612103, 2025). "CHRF also exerts its effects in various diseases through similar miRNA regulatory axes, including the CHRF/miR-489/MyD88 Axis, which is involved in cardiac hypertrophy, non-small cell lung cancer, and silicosis and is often associated with inflammatory responses, cell proliferation, and fibrosis." (PMID 40612103, 2025). "Some TLR/MyD88 signaling inhibitors also ameliorate cardiac hypertrophy." (PMID 37113698, 2023). "Besides, studies have demonstrated that heat shock proteins (HSPs), such as HSP60 and HSP70, induced cardiac hypertrophy by activating NF-κB through the TLR2/MyD88-dependent pathway in Dox-induced animal models." (PMID 37113698, 2023). "In contrast, some molecules and compounds negatively regulate cardiac hypertrophy by suppressing TLR4/MyD88 signaling, which includes protein molecules such as MD1 and anti-HSP70 antibody and compounds such as Ang II type 1 receptor (AT1-R) antagonist and liver × receptors agonist." (PMID 37113698, 2023). "It is reported that lncRNA cardiac hypertrophy-related factor (CHRF) acts as an endogenous sponge, thus downregulating miR-489 and thereby elevating the level of myeloid differentiation primary response gene 88 (Myd88) in cardiomyocytes, and finally it contributes to cardiac hypertrophy." (PMID 35990951, 2022). "Finally, lncRNA Chrf is upregulated in cardiac hypertrophy by targeting miR-489 and Myd88 in cardiac hypertrophy." (PMID 34360851, 2021). "Because MYD88 induces cardiac hypertrophy, CHRF regulates cardiac remodeling." (PMID 32792557, 2020). "B(a) P was reported to cause defect of cardiovascular development by aryl hydrocarbon receptor or up regulated of rbp4 and may results in cardiac hypertrophy by activating TLR4/MyD88 signal pathway." (PMID 30112104, 2018). "MYD88 is a gene known to be overexpressed in cardiac hypertrophy." (PMID 26978351, 2016). "In conclusion, evidence is presented that cardiac TLR2 and TLR4 signaling pathways may be key in renal I/R-induced cardiac hypertrophy and electrical dysfunction through mechanisms that involve MyD88 and NF-κB." (PMID 26448184, 2015). "TLR4 has been reported to induce myocardial hypertrophy via activation of MYD88 and NF-κB pathway." (PMID 25546437, 2014). "MYD88 absence in mice could improve post-MI survival and reduce cardiac hypertrophy." (PMID 38956669, 2024).
cardiac hypertrophy (continued). "Therefore, CHRF‐induced activation of MyD88 would aggravate the development of cardiac hypertrophy." (PMID 32969576, 2020). "Blockade of MyD88 reportedly exhibited beneficial effects in reducing hypertrophic response, whereas its overexpression activated the NF-κB pathway and subsequently contributed to cardiomyocyte apoptosis in pressure overload-induced cardiac hypertrophy in vivo." (PMID 33324685, 2020). "Moreover, they showed that MYD88 is a direct target of miR-489 in cardiac hypertrophy." (PMID 26978351, 2016). "The TLR4/MyD88/PI3K/Akt pathway has both adverse and protective effects on cardiac hypertrophy, probably due to the different PI3K isoforms." (PMID 37113698, 2023). "Other MyD88-dependent pathways include the TLR4/MyD88/CaMK II, TLR4/MyD88/PI3K/Akt, and TLR4/MyD88/MAPK pathways, showing that TLR4/MyD88 downstream is more complicated in regulating cardiac hypertrophy." (PMID 37113698, 2023). "Although Ang II activates both MyD88 and TRIF pathways, only the TRIF pathway is required to mediate hypertension and cardiac hypertrophy." (PMID 37113698, 2023). "Supportively, our results demonstrated the high expression of MyD88, NF-κB, and MMP9 in mice with myocardial hypertrophy." (PMID 35046797, 2021). "It has been reported that blocking MyD88, the downstream adapter protein for TLR4 signaling, significantly improves mortality and reduces oxidation-CaMK II expression and cardiac hypertrophy." (PMID 33324685, 2020). "In fact, its deficiency normalized the glucose transporter-4 (GLUT4) expression in cardiomyocytes and attenuated hypertrophic response to pressure overload, whereas TLR4 or MyD88 knockdown attenuated RBP4-induced insulin resistance and cardiac hypertrophy." (PMID 33324685, 2020). "Taken together, these results indicated that cardiomyocyte‐specific MyD88 knockout shows no significant protection in Ang II‐induced cardiac hypertrophy." (PMID 40682481, 2025). "It was reported that the TRIF-dependent pathway is shown to be a determinant in hypertension and cardiac hypertrophy, whereas the MyD88-dependent pathway is not responsible." (PMID 33324685, 2020). "In addition, the absence of MyD88 indirectly prevents post-myocardial infarction cardiac hypertrophy, inflammation, and oxidised Ca2+-calmodulin-dependent protein kinase (CaMKII) expression." (PMID 41325840, 2025). "Moreover, chronic intermittent hypoxia, the most characteristic pathophysiological change of obstructive sleep apnea syndrome, has been reported to induce cardiac hypertrophy in animal models, and the beneficial cardiac effects are produced by inhibition of the TLR4/MyD88/NF-κB pathway." (PMID 33324685, 2020).